NEU1 (neuraminidase 1)
Diseases named in the same sentence as NEU1 in open-access papers (continued):
Sharing a sentence is not in itself a finding about the gene and the disease.
infection (18 papers, 2014 to 2025). The state of being infected such as from the introduction of a foreign agent such as serum, vaccine, antigenic substance or organism. "Forced NEU1 overexpression in A549 cells using Ad-NEU1 infection diminished PI3K–MUC1-CD association compared with cells infected with Ad-GFP (lanes 3 versus 2)." (PMID 34688655, 2021). "We further examined the TLR4-TRIF association in Neu1-overexpressed and siglec-E silenced co-transfected cells followed by infection as measured by co-immunoprecipitation." (PMID 33763070, 2021). "During infection, either reduced Neu1 or enhanced siglec-E-TLR4 association ubiquitinates and degrades TLR4." (PMID 33763070, 2021). "This novel finding establishes a link between enhanced α2,3-linked sialic acids on TLR4 and reduced membrane-bound Neu1 which plays a significant role for inhibiting downstream signaling to establish successful infection in the host cells." (PMID 31649671, 2019). "Additionally, we reported reduced Neu1 during L. donovani-infection enhanced sialylation on TLR4 preventing its association with MyD88 resulting in an inappropriate cellular activation." (PMID 33763070, 2021). "Moreover, infection with L. donovani in Neu1-transfected cells showed enhanced TLR4-MyD88 association." (PMID 31649671, 2019). "Furthermore, infection of A549 cells with Ad-NEU1-G68V encoding a catalytically dead NEU1 mutant also diminished PI3K–MUC1-CD association (lanes 4 versus 2), indicating that NEU1 catalytic activity was not required for NEU1-mediated disruption of PI3K–MUC1-CD association." (PMID 34688655, 2021). "While the molecular mechanism of MUC1-ED desialylation mediated recruitment of NEU1 under Pa infection is still unclear." (PMID 38500102, 2024). "NEU1 inhibitors (oseltamivir and zanamivir) dampened neutrophil dysfunction and improved infection control as well as host survival in pulmonary infection." (PMID 38500102, 2024). "Treatments that target Neu-1 are predicted to be highly effective against infection with SARS-CoV-2, given the central role played by this enzyme in viral cellular entry and the induction of the CRS." (PMID 37174732, 2023). "In vitro infection of mouse J774.A1 macrophage cells with the obligate intracellular protozoan parasite, Leishmania donovani, reduced cell surface expression of NEU1 compared with uninfected controls." (PMID 35479093, 2022). "This intrigued us to investigate if modulation of Neu1 and siglec-E has a protective role in such degradation during infection." (PMID 33763070, 2021). "Overexpression of Neu1 followed by infection was able to prevent sialic acid siglec-E interaction through TLR4 desialylation." (PMID 33763070, 2021). "Combined with its catalytic role in generating a hyperadhesive, shed MUC1-ED decoy receptor, NEU1 offers a bipartite level of regulation over the airway epithelial response to Pa colonization and/or infection." (PMID 34688655, 2021). "To further confirm this dual regulation of TLR4 activation by Neu1/siglec-E, we separately overexpressed Neu1 and silenced siglec-E followed by infection." (PMID 33763070, 2021). "When Neu1 alone was overexpressed followed by infection, it led to the activation of the MyD88-pathway possibly due to TLR4-desialylation." (PMID 33763070, 2021). "Neu1-overexpression and siglec-E-silencing together followed by infection activated both MyD88 and TRIF-signaling through their enhanced TLR4-association." (PMID 33763070, 2021). "To address if such phosphorylation plays any role in surface translocation of Neu1 during infection, we immunoprecipitated Neu1 from the cell lysate of uninfected and infected cells with anti-Neu1 antibody and immunoblotted with anti-phosphotyrosine antibody." (PMID 31649671, 2019). "All these findings suggest that infection after Neu1 overexpression leads to TLR4 activation through its desialylation." (PMID 31649671, 2019).
infection (continued). "We observed decreased sialylation of TLR4 in the Neu1-transfected cells compared to mock transfection during infection." (PMID 31649671, 2019). "Subsequently, we observed enhanced phosphorylation of JNK, ERK and p38 along with enhanced nuclear translocation of a functional subunit of a transcription factor, NFκB in Neu1-transfected cells after infection." (PMID 31649671, 2019). "Moreover, on 3 d and 7 d post-infection, DEGs related to gut diseases were significantly affected, particularly Ceacam10, Tns4, Neu1, Serpina10, and Npas2." (PMID 39727670, 2025). "Accordingly, here, we attempted to address whether MyD88- and TRIF-mediated TLR4-signaling is dependent either on Neu1 or Siglec-E or both together through their action on the sialic acids of TLR4 during this infection." (PMID 33763070, 2021). "However, overexpressing Neu1 and silencing siglec-E together followed by infection was able to effectively upregulate both MyD88- and TRIF-dependent pathways of TLR4 activation." (PMID 33763070, 2021). "Thus our data indicate TLR4 is ubiquitinated and degraded during infection which is inhibited under Neu1 overexpressed or siglec-E silenced infected conditions." (PMID 33763070, 2021). "Therefore, reduced Neu1, as well as enhanced siglec-E-TLR4 association through interaction with sialic acids, down-regulated both MyD88- and TRIF-pathways during infection." (PMID 33763070, 2021). "In the presence of pathogens, endogenous neuraminidase-1 (sialidase-1, Neu-1) disrupts the interaction between the TLRs and the Siglecs, thereby activating the receptors and triggering an immune response during infection." (PMID 32575400, 2020). "We observed a decreased level of Neu1-phosphorylation in cell lysate during infection." (PMID 31649671, 2019). "Western blot analysis further revealed more cytosolic Neu1 during infection." (PMID 31649671, 2019). "Moreover, in order to pinpoint this important regulation by Neu1 during infection, we over expressed Neu1." (PMID 31649671, 2019). "Therefore, activation of TLR4 during L.donovani-infection may depend on two regulatory molecules (Neu1 and siglec-E) both of which identify the sialic acids on TLR4 as their target." (PMID 33763070, 2021). "However, the key player involved in TLR4 inhibition by Neu1 during this parasite-infection is largely unknown." (PMID 31649671, 2019). "Taken together our study ascertains the important role of enhanced cell surface Neu1 in TLR4 activation which has the potential to clear the parasite burden by generating a robust Th1 proinflammatory defense in the host cells which is otherwise reversed during infection." (PMID 31649671, 2019). "Furthermore, parasite-infection after Neu1 silencing resulted in a reverse scenario." (PMID 31649671, 2019). "NEU1 plays a critical role in activating cell surface Toll-like receptors (TLR), which are essential in triggering immune responses during infection." (PMID 35847014, 2022). "Another receptor important in immunomodulation that has been influenced by NEU1 is the activation of cell surface Toll-like receptors (TLR), which are critical in activating immune responses during infection." (PMID 35847014, 2022). "Accordingly, we overexpressed Neu1, which would desialylate and activate TLR4 and silenced siglec-E to prevent any binding with sialic acids which were followed by infection and confirmed by western blot analysis." (PMID 33763070, 2021). "Thus, we propose an inverse correlation of decreased Neu1 on the surface of these parasite-infected macrophages and enhanced sialic acids on TLR4 with reduced Neu1-TLR4 association and reduced activation, which is a prerequisite event for establishing a successful infection." (PMID 31649671, 2019).
infection (continued). "NEU1, which is commonly located at the lysosome and NEU3, found on cell surfaces, were induced during infection." (PMID 27389966, 2016). "Moreover, a reciprocal interplay between Neu1 and siglec-E differentially regulates MyD88- and TRIF-pathways through sialic acids on TLR4 as their common substrate during infection." (PMID 33763070, 2021). "NEU1 desialylates the MUC1-ED to unmask a cryptic Gly-Ser protease recognition site, thereby permitting the shedding of soluble MUC1-ED that functions as a decoy receptor to competitively inhibit Pa from establishing an invasive infection." (PMID 34688655, 2021). "Infection can boost inflammation through microbial sialidase, as we have recently reported, or as shown herein, by inducing translocation of host Neu1 to the cell surface to disarm the Siglec-mediated negative regulation of TLR function." (PMID 25187624, 2014).
cardiovascular disease (9 papers, 2021 to 2025). "Previous studies suggest that NEU1 is closely associated with the progression of several cardiovascular diseases." (PMID 34869700, 2021). "Notably, the expression of Neu1 transcript was remarkably elevated in damaged cardiomyocytes and tightly associated with a variety of cardiovascular disorders, indicating its crucial role in cardiac pathogenesis." (PMID 40411250, 2025). "This evidence suggests that NEU1 is an essential target for the treatment of cardiovascular disease." (PMID 40221400, 2025). "Current evidence suggests that Neu1 expression influences M1/M2 macrophage phenotype alterations in the context of cardiovascular diseases, indicating a potential role for Neu1 in macrophage polarization." (PMID 39346907, 2024). "This study combined with previous work suggests that NEU1 is a key driver of cardiovascular disease and is therefore a potential therapeutic target." (PMID 35002528, 2022). "Among them, NEU1 is the most highly expressed in the heart, involved in several cardiovascular diseases." (PMID 34977042, 2021). "Recent research has revealed that NEU1 plays an important role in cardiovascular disease." (PMID 40221400, 2025). "Whether NEU1, a recently identified inducer in various cardiovascular diseases, is involved in DOX cardiotoxicity remains unknown until now." (PMID 34977042, 2021).
metabolic disease (5 papers, 2021 to 2025). A congenital disorder (due to inherited enzyme abnormality) or acquired (due to failure of a metabolically important organ) disorder resulting from an abnormal metabolic process. "The dysregulation of NEU1 is associated with the onset and evolution of metabolic diseases, as NEU1 deficiency can lead to cellular aberrations in glucose, lipid, and protein metabolism, which in turn influences the trajectory of metabolic diseases." (PMID 39194692, 2024). "The increasing evidence supporting the therapeutic potential of NEU1 inhibitors positions them as an important agent in advancing treatment paradigms for complex diseases such as Alzheimer’s and metabolic disorders." (PMID 40573316, 2025). "Taken together, these results highlight that Nrf2 deletion exacerbates metabolic disorders phenotype in a NEU1‐dependent manner." (PMID 40411250, 2025). "In this part, the implication of sialidases, and notably NEU-1, in several metabolic diseases will be described." (PMID 36230790, 2022). "NEU1 plays a pivotal role in the biological effects mediated by EDP and the ERC in various vascular and metabolic diseases." (PMID 34903296, 2021).
respiratory diseases (2 papers, 2019 to 2024). "NEU1 activity is needed to sustain a variety of biological processes in the respiratory system, while NEU1 deficiency or dysfunction has been implicated in the abnormal metabolism of alveolar surface-active substances, resulting in respiratory diseases." (PMID 39194692, 2024).
neurodegenerative disease (1 paper, 2025). A disorder of the central nervous system characterized by gradual and progressive loss of neural tissue and neurologic function. "Additionally, alterations in NEU1 activity have been associated with several pathological conditions, including neurodegenerative diseases and cancer, where dysregulation of sialylation can lead to altered cell behavior and disease progression." (PMID 40573316, 2025). "This interplay between EVs, NEU1 activity and cellular responses highlights the importance of glycosylation in the pathophysiology of neurodegenerative diseases." (PMID 40573316, 2025). "The interplay between NEU1 and various signaling pathways, including those involved in inflammation and cellular stress responses, highlights the potential for targeted pharmacological interventions to recalibrate NEU1 activity in the context of neurodegenerative diseases." (PMID 40573316, 2025).
urological disease (1 paper, 2024). "In another urological disease context, evidence shows that NEU1 can inhibit the progression of human bladder cancer, mainly by dampening signal transduction mediated by fibronectin/integrin α5β1 and the Akt signaling pathway, culminating in reduced Akt activation." (PMID 39194692, 2024).
NEU1 also shares sentences with these, for which no sentence is quoted: mucolipidosis I (6 papers); cholera (4); abscesses (3); type 2 diabetes (3); developmental delay (2); dilated cardiomyopathy (2); gas gangrene (2); genetic diseases (2); glycoproteinosis (2); hypertrophic cardiomyopathy (2); immune disorders (2); immune thrombocytopenia (2); kidney damage (2); kidney diseases (2); non-alcoholic fatty liver diseases (2); non-alcoholic steatohepatitis (2); pancreatic ductal adenocarcinoma (2); Type 1 diabetes (2); acute myocardial infarction (1); airway hyperresponsiveness (1); allergic asthma (1); ankylosing spondylitis (1); autism spectrum disorder (1); autoimmune disorders (1); autosomal recessive inherited disorder (1); bacteremia (1); bacterial vaginosis (1); balanoposthitis (1); bipolar disorder (1); Bovine mastitis (1).
A further 38 diseases each share a sentence with NEU1 in 1 paper.